ADAMTS4 (ADAM metallopeptidase with thrombospondin type 1 motif 4)
Diseases named in the same sentence as ADAMTS4 in open-access papers (continued):
Sharing a sentence is not in itself a finding about the gene and the disease.
acute lymphoblastic leukemia (1 paper, 2025). Leukemia with an acute onset, characterized by the presence of lymphoblasts in the bone marrow and the peripheral blood. "ADAMTS4 rs41270041 polymorphism is associated with muscle function deficit in childhood acute lymphoblastic leukemia." (PMID 40002887, 2025).
aortic stenosis (1 paper, 2014). Aortic valve stenosis is a aortic valve disease caused by the incomplete opening of the aortic valve. "ADAMTS4 represents a promising novel therapeutic target in patients with aortic stenosis." (PMID 24595230, 2014).
ascending aortic aneurysm (1 paper, 2021). "Previously, we showed that ADAMTS-4 contributes to sporadic ascending aortic aneurysm development in mice." (PMID 35052435, 2021).
brain tumours (1 paper, 2006). "Until recently, the ADAMs and ADAMTS genes were relatively understudied in brain tumours (and other cancers), however, recent reports have suggested roles for ADAMTS-4, TS-5 and ADAM-12 in GBM, where these proteases are overexpressed." (PMID 16570050, 2006).
Breast Invasive Carcinoma (1 paper, 2025). "The Breast Invasive Carcinoma TCGA PanCancer Atlas dataset was used to identify 48 VPP cases and 66 VPW cases based on the expression of VCAN, ADAMTS4, and TIMP3." (PMID 40361362, 2025).
breast tumors (1 paper, 2012). "Moreover, a few genes involved in modulation of the extracellular matrix (ADAMTS4, MMP1, MMP3, and angiogenesis (MFAP5, SFRP2, SRPK1, VEGF, and CHI3L1) were found to be expressed at higher levels in the primary breast tumors compared with the bone metastases." (PMID 23174366, 2012).
cavernomas (1 paper, 2026). "This process has been shown in murine cavernomas and possibly mediated by the upregulation of genes involved in extracellular matrix reorganization, such as ADAMTS4." (PMID 41596430, 2026).
choriocarcinoma (1 paper, 2019). An aggressive malignant tumor arising from trophoblastic cells. "Lee18 and Minobe19 observed that the different expression of ADAMTS4 involves in the process of choriocarcinoma and Ewing's sarcoma." (PMID 31663692, 2019).
dissection (1 paper, 2023). The separation and isolation of tissues for surgical purposes, or for the analysis or study of their structures. "Three studies found increased ADAMTS4 levels in aortic tissues from TAAD patients, while one study also found higher ADAMTS4 levels in the serum of type A acute dissections compared to controls, with a good diagnostic value (sensitivity: 94.59%; specificity: 97.06%)." (PMID 37569511, 2023).
epilepsy (1 paper, 2025). A brain disorder characterized by episodes of abnormally increased neuronal discharge resulting in transient episodes of sensory or motor neurological dysfunction, or psychic dysfunction. "To further investigate the association between OL development and epilepsy, we examined the Adamts4 KO mouse line, which has a mild OL differentiation phenotype in the hippocampus." (PMID 40673958, 2025).
fatty liver (1 paper, 2023). "The two metallopeptidases ADAMTS1 and ADAMTS4 were related to ATH in practically all of the databases we consulted, while their relationship with the liver was shared between oncologic processes and fatty liver." (PMID 36835545, 2023).
Granuloma (1 paper, 2022). A compact, organized collection of mature mononuclear phagocytes, which may be but is not necessarily accompanied by accessory features such as necrosis. "ADAMTS4 has also been shown to increase tumour growth, which correlates with the increased size of the granulomas from trickle-infected animals." (PMID 36569914, 2022).
head and neck cancer (1 paper, 2017). A primary or metastatic malignant neoplasm affecting the head and neck. "Of note, ADAMTS-4 is expressed at lower level than ADAMTS-5 in tumors of the larynx and in the metastatic loci of head and neck cancers." (PMID 28099917, 2017).
ischemic stroke (1 paper, 2024). A stroke disorder caused by obstruction of blood flow to the brain, due to thrombotic (local blood clot formation) or embolic (due to a blood clot or other material traveling from another site) event. "On the other hand, ADAMTS4 seems to decrease inflammation after ischemic stroke by increasing the number of microglia expressing arginase-1, a marker of alternatively activated cells with anti-inflammatory functions." (PMID 37378751, 2024).
lentivirus infection (1 paper, 2021). Virus diseases caused by the Lentivirus genus. "Immunofluorescence experiments further revealed that OA progression, as assessed primarily by MMP13, ADAMTS4, and COL2A1, was inhibited in HCs following circRSU1 shRNA lentivirus infection." (PMID 33408787, 2021).
liver cancer (1 paper, 2019). An epithelial or non-epithelial malignant neoplasm that arises from the liver. "Through a hospital‐based case‐control study, we explored the linkage between ADAMTS4 SNPs and the risk of HCC in Guangxi Zhuang Autonomous Region, a high incident area of liver cancer in China." (PMID 31663692, 2019).
metastatic disease (1 paper, 2022). "ADAMTS-4, a member of the ADAMTS family of metalloproteinases, was highly expressed in localized samples compared to metastatic disease (localized mean = 4.83, metastatic mean = 2.31, p = 1.8 × 10–9)." (PMID 36371231, 2022).
multiple myeloma (1 paper, 2009). "The combination of PPARγligands with 9-cis retinoic acidincreases the killing of multiple myeloma cells and cooperatively suppressesexpression of ADAMTS4/Aggregecanase-1, a protein stimulated by IL-1 thaterodes articular cartilage in arthritic disease." (PMID 19461950, 2009).
myocardial infarction (1 paper, 2022). Gross necrosis of the myocardium, as a result of interruption of the blood supply to the area, as in coronary thrombosis. "To our surprise, we have also detected the expression of Adamts4 in vivo murine model of myocardial infarction (MI), localized in adult cardiomyocytes." (PMID 35701493, 2022).
neuroblastoma (1 paper, 2023). Neuroblastoma (NB) is the most common solid, extracranial childhood tumor. "ADAMTS4 is expressed in the central nervous system, and our cell-based assay revealed that neuroblastoma cell secretes APP669-711." (PMID 36721026, 2023).
ovarian carcinoma (1 paper, 2016). A malignant neoplasm originating from the surface ovarian epithelium. "Concerning ADAMTS 4, we observed that ADAMTS 4, 90 kDa (full-length or unprocessed) in the cell lysate and ADAMTS 4, 62 kDa (fragmented or processed) is detected in the conditioned medium of both ovarian cancer cell lines studied." (PMID 26916548, 2016).
psoriatic arthritis (1 paper, 2021). Joint inflammation associated with psoriasis. "Using a panel of eight biomarkers (PIIANP, TIMP-1, ADAMTS-4, CCL2, IP-10 and TGF-β3), this model distinguishes between OA, knee injury and inflammatory knee arthritis (i.e. RA or psoriatic arthritis) with almost 100% efficacy." (PMID 34804052, 2021).
sarcopenia (1 paper, 2025). Progressive decline in muscle mass due to aging which results in decreased functional capacity of muscles. "Therefore, we suggested that the decreased expression of ADAMTSs, especially ADAMTS4, could contribute to the compromised regenerative potential of skeletal muscle stem cells by promoting fibronectin and versican deposition in CS-exposed mice, thereby leading to COPD-related sarcopenia." (PMID 40002887, 2025).
ulcerative colitis (1 paper, 2023). An inflammatory bowel disease involving the mucosal surface of the large intestine and rectum. "Immunohistochemical analysis of ADAMTS-1, ADAMTS-4, ADAMTS-5, and IL-17 A protein in the colon tissues of healthy human control and those with ulcerative colitis." (PMID 37798683, 2023).
uveal melanoma (1 paper, 2021). A melanoma derived from melanocytes of the uveal tract. "Adamts4 has been linked to stemness in uveal melanoma through modulating crosstalk between the cells and their adjacent ECM30." (PMID 33953351, 2021).
ZIKV infection (1 paper, 2023). "On the other hand, mRNA levels for MMP-9, ADAMTS-4, and ADAMTS-5, which have been reported associated with PNN degradation, and gelatinase/collagenase activity were not significantly elevated in the brain during ZIKV infection." (PMID 37496706, 2023).
tumor (25 papers, 2006 to 2026). "The inactive ADAMTS4 enzyme or only its C-terminus domain inhibits melanoma growth and its angiogenesis associated with tumor cell apoptosis." (PMID 35053160, 2021). "Regarding tumor-related processes, both ADAMTS-4 and ADAMTS-5 are associated with a protumor role." (PMID 31508361, 2019). "ADAMTS4’s involvement in tumor angiogenesis is closely linked to its catalytic activity." (PMID 24213506, 2012). "The full length ADAMTS-4 and its catalytically active N-terminal 53 kDa (auto)catalytic fragment both promote tumor growth and angiogenesis." (PMID 36144730, 2022). "An increase in serine proteases HTRA3, myeloblastin and lactotransferrin in all stages and metalloproteinases (MMP-9, ADAMTS4 and neutrophil elastase) in CC NM and CC M, supports degradation of the stroma surrounding the tissues as the tumor progresses." (PMID 31889941, 2019). "Our results showed that ADAMTS4 rs538321148 and rs1014509103 polymorphisms were linked with the upregulation of ADAMTS4 expression, increasing tumor MVD and metastasis risk, and tumor dedifferentiation and progression." (PMID 31663692, 2019). "The clusters 1, 7 and 8 highly expressed steroidogenic genes STAR as well as tissue remodeling genes HAS1, ADAMTS1 and ADAMTS4, consistent with theca-stromal cells from ovary, which might be included from non-tumor tissues from ovaries." (PMID 34257564, 2021). "The full length of ADAMTS4 promotes tumor angiogenesis and subsequently tumor growth." (PMID 35053160, 2021). "This could indicate that ADAMTS-4 exerts a less relevant role than ADAMTS-5 in the metastatic processes of certain tumor types." (PMID 28099917, 2017). "- ADAMTS4 C-terminal ancillary regions inhibit tumor angiogenesis." (PMID 24213506, 2012). "In Ewings sarcoma, high expression of ADAMTS4 is a potential tumor marker." (PMID 24213506, 2012). "For example the predominant role of ADAMTS-8 may be antiangiogenesis, necessitating silencing in tumours, whereas the predominant role for ADAMTS-4 and TS-5 may be ECM degradation necessitating up-regulation." (PMID 16570050, 2006). "Furthermore, in a tumor environment, both ADAMTS4 and OPN are overexpressed in colon cancers." (PMID 34795242, 2021). "Core genes with a higher DC (> 8), EC (> 0.06), LAC (> 2.0), BC(> 200), and NC(> 0.3) in the enriched modules were also expressed differentially in TCGA‐CHOL data (36 tumor samples and 9 adjacent cancer samples), including FGF2, IGF1, CAV1, SPON1, and ADAMTS4." (PMID 40304434, 2025). "Increased expression of TIMP1, MMP1, AGRN, UNC5A, and ADAMTS4 was observed, while the expression of UNC5C, TINAG, SPOCK3, and ITGA7 was reduced in the normal FHC cells compared to the HCT8 tumor cells." (PMID 39011483, 2024). "Adamts4 has been shown to contribute to the development and progression of CRC, especially due to its effects on tumor growth, the regulation of macrophages, and the influence on the inflammatory microenvironment in cancer." (PMID 35457963, 2022). "From a transcriptomic perspective, tumour endothelial cells upregulate angiogenesis-related genes, such as CD99, KLF10, and ADAMTS4, while losing scar tissue-related Notch molecule HES4 and antigen presentation molecule HLA-DRA." (PMID 33532508, 2021). "Highly interrelated nodes, such as COL1A1, COL1A2, POSTN, ADAMTS4, and CD34, have been reported to regulate the tumor microenvironment and promote the growth, angiogenesis, and invasion of malignancies." (PMID 31480381, 2019). "They observed that both ADAMTS4 full‐length and N‐terminal autocatalytic fragment (NTAF) can promote angiogenesis and tumor growth in mice; whereas their mutant types or C‐terminal fragment displayed converse role." (PMID 31663692, 2019).
tumor (continued). "Hence, it is possible that ADAMTS-4 and mainly ADAMTS-5 play a key role in tumor progression to higher stages of CRC by degrading ECM, so as to facilitate cancer cell invasion, in a similar manner as it has been previously demonstrated for hyaluronidase." (PMID 25786261, 2015). "Fifth, although the effects of ADAMTS4 SNPs on OS status were investigated among these patients with HCC, their effects on tumor occurrence‐free survival were not estimated." (PMID 31663692, 2019).
cancer (16 papers, 2006 to 2025). A tumor composed of atypical neoplastic, often pleomorphic cells that invade other tissues. "ADAMTS-1, −3, −5, −8 and −18 were down-regulated in cancer tissues whilst ADAMTS-4, −6, −10 and −14 were overexpressed in cancer tissues." (PMID 33063817, 2020). "RT-PCR and western blotting analyses in cultured cells of three different cancer cell lines revealed that expression levels of ADAMTS-5 were stronger related to cancer aggressiveness, as compared to ADAMTS-4." (PMID 25786261, 2015). "From the results of our study in CRC tissue and cells, we conclude that ADAMTS-4 and -5 expression positively correlates with cancer progression, whereas the anti-angiogenic ADAMTS-1 and -20 were found to be down-regulated and degraded." (PMID 25786261, 2015). "In CRC, the expression levels of ADAMTS-4 and -5 were relatively decreased in early cancer stages (A, B) and the localization of the metalloproteinases was primarly at stroma cells." (PMID 25786261, 2015). "Our data suggest a positive correlation between ADAMTS-4 and -5 expression and cancer progression, in contrast with the anti-angiogenic members of the family, ADAMTS-1 and -20, which were found to be down-regulated." (PMID 25786261, 2015). "The different expression levels of ADAMTS-1 and-20 in CRC, despite their individual differences, further differentiate their implication in cancer, as compared to ADAMTS-4 and -5." (PMID 25786261, 2015). "Increased expression of ADAMTS4 was observed in several human cancers such as breast, head and neck squamous cell carcinoma and human glioblastoma." (PMID 24213506, 2012). "Preliminary data in our lab also indicates widespread expression of ADAMTS4 protein in human cancers." (PMID 24213506, 2012). "ADAMTS-4 has also been demonstrated to have dual functions in cancer." (PMID 36144730, 2022). "Collectively, these findings imply that ADAMTS4 SNPs could affect the expression and function of ADAMTS4 and ultimately increase HCC risk and shorten the prognosis of patients with this cancer." (PMID 31663692, 2019). "Of all the differentially expressed genes, secreted signaling proteins Tgfb2, Il-6, Cxcl1, and Ctgf and metallopeptidases Mmp13, Adamts4, and Adamts5 were of particular interest, as these genes have previously been shown to play a role in regulating cancer migration and invasion and bone remodeling." (PMID 27600237, 2015). "Finally, ADAMTS-4 and -5 displayed similar expression pattern during cancer progression." (PMID 25786261, 2015). "Apart from its active form, ADAMTS-4 was also present in its latent form, while ADAMTS-5 was constantly present in its active form during cancer progression." (PMID 25786261, 2015). "The results of this study support the notion that ADAMTS-4 and -5 are over-expressed in CRC possibly for tissue disruption that would facilitate cancer cell invasion and metastasis." (PMID 25786261, 2015). "Hence, it could be suggested that among these two enzymes, ADAMTS-5 was over-expressed mainly in mediate/highly-aggressive cancer cells, while ADAMTS-4 performed a wider range of expression, regardless of cancer aggressiveness." (PMID 25786261, 2015).
infection (6 papers, 2017 to 2025). The state of being infected such as from the introduction of a foreign agent such as serum, vaccine, antigenic substance or organism. "Live and heat-inactivated L. reuteri KBL346 increased the expression level of Adamts4, which promotes recovery after infection, and decreased that of Tlr2." (PMID 38949757, 2024). "Of note, the disruption in PNN formation during infection was associated with increased expression of MMP-12 and -19 but not MMP-9 or ADAMTS-4 or -5, which have been previously shown to be increased in some disorders where established PNNs are disrupted." (PMID 37496706, 2023). "We found that overexpression of ERRγ via infection with Ad-Esrrg significantly elevated the mRNA levels and extracellular secreted protein levels of MMP3 and MMP13, without affecting ADAMTS4 or -5." (PMID 29247173, 2017).
cardiac disease (2 papers, 2022 to 2023). "This confirms that Adamts4 is also induced in humans who have a history of cardiac diseases like DCM or have suffered MI." (PMID 35701493, 2022). "Therefore, future studies on the roles of ADAMTS4 in cardiac disease should include blood pressure measurements and aortic examinations." (PMID 37216909, 2023).
inflammation (1 paper, 2020). Aberrant reaction of the microcirculation characterized by movement of fluid and leukocytes from the blood into extravascular tissues. "Synovial fluid ADAMTS4 activity is correlated with synovial inflammation in patients undergoing arthroscopy; thus, the decrease in Adamts4 mRNA we observed may be indicative of a specific modulation of the inflammatory response by MSCs." (PMID 32059749, 2020).
kidney disease (1 paper, 2022). "The significance of such correlation is yet to be explored, but presumably, ADAMTS-4 might be expressed by activated circulating macrophages as a part of kidney disease." (PMID 35328201, 2022).
neurodegenerative disease (1 paper, 2016). A disorder of the central nervous system characterized by gradual and progressive loss of neural tissue and neurologic function. "ADAMTS-4 is a metalloproteinase specialized in the degradation of chondroitin sulfate proteoglycans (CSPGs) whose functions during neurodegenerative diseases, including ALS, have not been investigated." (PMID 26809777, 2016).
ADAMTS4 also shares sentences with these, for which no sentence is quoted: cardiovascular diseases (4 papers); chorioamnionitis (2); juvenile idiopathic arthritis (2); lung fibrosis (2); Airway obstruction (1); Anxiety (1); Aortic dissection (1); asthma (1); autoimmune disease (1); chronic kidney disease (1); coronary artery diseases (1); COVID-19 (1); depression (1); dilated cardiomyopathy (1); Ewing sarcoma (1); experimental autoimmune encephalomyelitis (1); frontotemporal dementia (1); hearing loss (1); intervertebral disc disorders (1); lung carcinoma (1); major depressive disorder (1); membranous nephropathy (1); osteoporosis (1); pulmonary arterial hypertension (1); reactive arthritis (1); rheumatic diseases (1); scoliosis (1); skeletal dysplasia (1); skeletal system disease (1); spinal cord injury (1).
A further 5 diseases each share a sentence with ADAMTS4 in 1 paper.